DLC1 (DLC1 Rho GTPase activating protein)
Diseases named in the same sentence as DLC1 in open-access papers (continued):
Sharing a sentence is not in itself a finding about the gene and the disease.
breast carcinoma (continued). "Meanwhile, the reintroduction of DLC-1 in metastatic breast cancer cell line leads to reduction of migration and invasion properties in both in vitro and in vivo models." (PMID 26260454, 2015). "In this framework, overexpression of DLC1 was shown to exhibit inhibitory effects on cell growth and proliferation in hepatocellular and breast cancer." (PMID 24627003, 2014). "A similar phenotype was previously seen when an amino terminal deleted form of Dlc1 or just the RhoGap domain were transfected into breast cancer cells." (PMID 22792269, 2012). "In the past few years, evidence supporting the metastasis suppressor function of DLC1 has been generated with breast cancer, and HCC cells." (PMID 22580498, 2012). "In our target prediction study, we have observed that miR-495 binds to 3’UTR segment of DLC1 and metastatic suppressor gene in breast carcinoma call line M4A4." (PMID 19898689, 2009). "Suppressing DLC1 degradation could inhibit the migration through the DLC1/RhoA pathway in breast cancer." (PMID 35223504, 2022). "In this study, we discovered new regulators of DLC1 proteostasis in breast cancer cell lines." (PMID 35322810, 2022). "The expression level of the enhancer of zeste homolog 2 (EZH2), deleted in liver cancer 1 (DLC1), is negatively correlated in breast cancer, where the upregulation of EZH2 and the downregulation of DLC1 have been reported in breast cancer tissue and MDA-MB-231 cells." (PMID 34298639, 2021). "Conversely, downregulation of DLC1 via genetic and epigenetic mechanisms occurs frequently in a variety of cancers, including liver cancer, lung cancer, colorectal cancer, prostate cancer, and breast cancer." (PMID 32214200, 2020). "Therefore, it is assumed that KIBRA and ER via DLC1 optimally stimulate the growth of breast cancer cells." (PMID 29793439, 2018). "In breast cancer, the reductions were 4-fold for DLC1 and 2-fold for both DLC2 and DLC3." (PMID 27174913, 2016). "Several studies of breast cancer have found that chromosomal region 8p22, where Dlc1 maps, is a site of frequent deletions without a loss of heterozygosity, suggesting the location of a haploinsufficient tumor suppressor(s)." (PMID 26353792, 2015). "Previous results had suggested that the chromosome region 8p22, where Dlc1 maps, may contain a haploinsufficient tumor suppressor gene in breast cancer." (PMID 26353792, 2015). "Likewise, reintroduction of DLC1 breast cancer cell lines results decreased tumorigenic growth, supporting its major role as a tumor suppressor." (PMID 23988121, 2013). "Together, these data suggest the DLC1 may play an important role in the development of distant metastasis and mortality of breast cancer patients." (PMID 23056464, 2012). "A similar scenario may underlie the pro-migratory behavior of DLC1-negative cancer cell lines, including breast cancer." (PMID 40354489, 2025). "Overall these results suggest that Dlc1 may be an important tumor suppressor in breast cancer." (PMID 26353792, 2015). "In addition, AI at chromosome 8p22 in the DLC1 gene region is associated with breast cancer mortality, independent of other pathological factors while AI at chromosome 13q14 is associated specifically with late mortality." (PMID 23056464, 2012). "Using breast cancer cells, we combined cellular assays with mathematical modeling to extend an existing EMT model to include DLC1." (PMID 40354489, 2025). "DLC1 was found to repress PTHLH transcription and secretion and eventually lead to decrease breast cancer bone metastasis." (PMID 36185184, 2022). "A previous study supports the role of DLC1 as an inducer of apoptosis in NSCLC and as a metastasis suppressor in breast cancer cells." (PMID 31681566, 2019). "The first evidence of the function of KIBRA in breast cancer cells came from the finding that KIBRA controls estrogen receptor transcriptional activity and binds to the DLC1." (PMID 29793439, 2018).
breast carcinoma (continued). "Deleted in liver cancer 1 (DLC1), another Rho GTPase-activating protein, has been reported to interact with PTEN to regulate the migration of breast cancer cells." (PMID 29867200, 2018). "Here, we explore the functional relations between DLC1 and CDK6 in breast cancer survival at both germ line genetic and gene expression levels." (PMID 25425654, 2014). "The gene expression of DLC1 is positively influenced by that of CDK6 in ER-positive breast tumors, indicating the importance of ER in the interactions between DLC1 and CDK6 in breast cancer." (PMID 25425654, 2014). "Here, we explore the influence of the synergistic effect of DLC1 and CDK6 on human breast cancer survival at the genetic, transcriptional, and translational levels." (PMID 25425654, 2014). "The results help us in understanding the cooperation between DLC1 and CDK6 in breast cancer, which, once experimentally verified, contribute to personalized medicine and can be applied for clinical use." (PMID 25425654, 2014). "We are the first to report such synergistic effects of DLC1 and CDK6 on breast cancer survival at the transcriptional level, the overdominant model fitted by the SNP pair, and the dominant negative effect at the translational level." (PMID 25425654, 2014). "DLC1 was reported to suppress parathyroid hormone-like hormone (PTHLH) transcription and secretion through Rho-TGF-β crosstalk, leading to attenuate osteoclast maturation and reduce breast cancer bone metastasis." (PMID 36185184, 2022). "DLC1 and DLC2 copy number loss percentages in the TCGA breast carcinoma dataset were 33% and 18% respectively (data not shown)." (PMID 27174913, 2016). "Another study, using matched malignant and nonmalignant human breast cancer cell lines, showed that the nonmalignant line had Dlc1 transcript levels 3-fold greater than the malignant clone." (PMID 26353792, 2015). "In particular, one SNP pair, rs561681 (DLC1) and rs3731343 (CDK6), was identified to have a synergistic effect on breast cancer patient survival, as verified in two independent cohorts, and these SNPs were each associated with the expression of the corresponding gene." (PMID 25425654, 2014). "An interaction between DLC1 and CDK6 was found to affect breast cancer survival." (PMID 25425654, 2014). "In addition to estrogen signaling and resistance to therapy, 7 of the identified genes have been previously associated with cell cycle regulation (CCND1, CDKN1A, CDKN1B, and CDKN2A) and breast cancer aggressiveness (CLDN7 and DLC1)." (PMID 22616718, 2012). "A link between SGCZ, KIAA1456 or C8orf48 and breast cancer has not been established, however, DLC1 has been shown to inhibit cancer cell growth and been implicated as a tumor suppressor." (PMID 23056464, 2012). "The ability of flavone to restore DLC1 expression and, consequently, to suppress metastatic breast cancer cell proliferation is not an isolated example." (PMID 22580498, 2012). "Ectopic expression of DLC1 was found to suppress cell migration and invasion in HCC, non-small cell lung cancer, breast cancer, lung cancer, ovarian cancer cell line models, and overexpression of DLC1 in metastatic breast cancer cell line could attenuate size and incidence of pulmonary metastases." (PMID 18648664, 2008). "However, that is a distinct phenomenon in breast cancer, as p38 inhibition neither reduced cytoplasmic EZH2 nor increased DLC1 protein in lung cancer cells." (PMID 34862367, 2021).
liver cancer (31 papers, 2009 to 2023). An epithelial or non-epithelial malignant neoplasm that arises from the liver. "On the genetic level, deleted in liver cancer 1 (DLC1) is a tumor suppressor gene, whose allele was found to be lost in about 50% of liver cancers." (PMID 34771537, 2021). "Given the frequency of DLC1 loss in liver cancer, unravelling the signaling cascades initiated by DLC1 appears to be an important task to tackle." (PMID 33255630, 2020). "Loss of DLC1 leads to an activation of RhoA, and cooperates with oncogenic Myc in a mouse model of liver cancer." (PMID 27104658, 2016). "The Deleted in liver cancer one (Dlc1) tumor suppressor gene encodes a RhoGTPase activating protein (RhoGAP)." (PMID 22792269, 2012). "Deleted in liver cancer 1 (DLC-1) has a great active role in inactive tumor suppressor gene deletion in hepatic cancer because it is induced by promoter methylation." (PMID 38322013, 2023). "We focused our siRNA screen on cell migration and thereby confirmed a metastasis suppressive role for MSRA, NAT1, PPP2CB, and DLC1 in liver cancer." (PMID 38134284, 2023). "Examining the allelic alteration patterns of the DLC1 locus revealed a larger portion of samples from melanoma patients with gain in copy number of DLC1 than that of liver cancer patients." (PMID 32214200, 2020). "MKL1 can also activate the transcription of deleted in liver cancer (DLC1) and myoferlin to defy oncogenic senescence and preserve cancer cell viability." (PMID 32984327, 2020). "DLC1 is a Rho GTPase-activating protein (RhoGAP) that is heterozygously deleted in 50% of liver cancers." (PMID 33255630, 2020). "The first of these is rs2410116 (p = 4.06E−07), which is mapped into a gene desert region 300.2 kbp upstream of the gene encoding Rho GTPase Activating Protein (also known as deleted in liver cancer; DLC1)." (PMID 30563984, 2018). "Rho GAP known as DLC1 (“deleted in liver cancer”) is considered as a tumor and metastasis suppressor gene for several human cancers." (PMID 27588930, 2017). "This differential RHOA activity determines polarized NC morphology and motility, and is regulated by the asymmetrically localized RhoGAP Deleted in liver cancer (DLC1) in the cytoplasm at the cell front." (PMID 29084958, 2017). "DLC1 can be phosphorylated upon expression of AKT or insulin induction in liver cancer cell lines, and S567A mutant (phosphodefective mutant of DLC1) inhibits colony formation in cancer cells and tumor formation in nude mice." (PMID 28903430, 2017). "These preliminary data supported the idea that DLC1 is a tumor suppressor that is silenced in meningiomas, similar to other human tumors such as nasopharyngeal, pancreatic, colon, prostate and liver cancer." (PMID 27614886, 2016). "The GAP DLC1 (deleted in liver cancer) is a tumor suppressor frequently downregulated in many cancer types either by deletion or epigenetic silencing." (PMID 27104658, 2016). "A p122RhoGAP/DLC-1 is also recognized as a tumor suppressor, which is frequently down-regulated in several malignant cancers, such as colorectal, breast, prostate, and liver cancers." (PMID 26624289, 2015). "A major breakthrough towards a targeted therapy of HCC was the discovery that the tumour suppressor DLC1 is deleted in 50% of liver cancers." (PMID 23853104, 2013). "In that respect, a combined therapeutic approach, targeting both MYC and DLC1 signaling networks, have realistic potential to improve the treatment of liver cancer." (PMID 22580498, 2012). "Deletion in liver cancer gene (DLC1) and phosphorylated focal adhesion kinase (p-FAK) have recently been reported as metastasis-related genes." (PMID 22272086, 2011). "Two members of the family, RhoA and RhoC, have been implicated in metastasis, and the expression of the Rho-GTPase-activating protein (Rho-GAP) DLC1 (for Deleted in Liver Cancer 1) is suppressed in liver cancer tissue and in a number of other cancers." (PMID 21234284, 2010).
liver cancer (continued). "Predicted target DLC1, deleted in liver cancer, is found to act as tumor suppressor in hepatocellular and non-small cell lung carcinoma." (PMID 19898689, 2009). "One of the genes that were highly down-regulated in our study was DLC1 (deleted in liver cancer 1), showing more than an 8-fold change and a p-value ≤ 0.0001, and it has been verified from the literature search that a low expression of DLC1 is associated with gastric cancer." (PMID 36984515, 2023). "Although HCC is the second leading cause of cancer mortality in the world, and loss of the tumor suppressor deleted in liver cancer 1 (DLC1) occurs in 50% of liver cancers, the signaling pathways downstream of DLC1 that mediate liver carcinogenesis are relatively poorly understood." (PMID 34771537, 2021). "Although it has been shown that deleted in liver cancer 1 (DLC1) acts as a tumor suppressor whose allele is lost in 50% of liver cancers, alterations in gene expression initiated by DLC1 loss have not yet been the primary focus of liver cancer research." (PMID 34771537, 2021). "Nevertheless, a detection of DLC-1 as a therapeutic indicator or prognostic markers in liver cancers have litter been elucidated and the role and mechanism of DLC-1 in liver cancer especially in the invasion and metastasis process remains to be fully eclucidated." (PMID 26846339, 2016). "Moreover, a liver cancer suppressor gene named DLC-1, which induces apoptosis and exerts inhibitory effects on the cell proliferation of HCC cells, is located in a site of ∼24 Mb upstream of the two SNPs (rs2275959 and rs37821974) on 8p12." (PMID 24987808, 2014). "Given that BMP signaling and a human homolog of Cv-C, Deleted in liver cancer (DLC1), act as tumour suppressors in a variety of contexts, a similar coupling mechanism may be operated in tissue homeostasis as well as tissue morphogenesis." (PMID 23555308, 2013). "We previously reported that the RhoA up-stream regulators, DLC1 and DLC2 (deleted in liver cancer 1 and 2), were frequently down-regulated in human HCC by genetic deletion and epigenetic silencing." (PMID 25909223, 2015). "B; 2a, b; 3a, b and 4a, b, positive staining rates of DLC-1, Rho A, ROCK2 and moesin in liver cancer tissue samples were 38.75, 78.75, 75.00 and 86.25 % respectively, which was significantly different from those in normal mucosa (83.75, 43.75, 40.00 and 66.25 %) (P < 0.001)." (PMID 26846339, 2016). "Therapeutic interventions, which would simultaneously target signaling pathways governing both DLC1 and MYC functions in hepatocarcinogenesis, could result in progress in the treatment of liver cancer." (PMID 22580498, 2012). "In the present study, we found that hepatic neoplasm was an age-related disease, and resveratrol inhibited age-dependent spontaneous tumorigenesis by SIRT1-mediated post-translational modulations of K-Ras, FoxOs and DLC1 to proliferation and apoptosis in the annual fish." (PMID 28903430, 2017).
lung carcinoma (21 papers, 2008 to 2025). "DLC-1 acts as a tumor-suppressor gene, and its low expression was associated with poor prognosis in lung cancer." (PMID 32316405, 2020). "For example, poor prognosis was reported to be associated with low DLC1, low CDKN2A/B and high CDK4 in lung cancer, and low DLC1, low CDKN2B, and high CDK6 in colon cancer." (PMID 25425654, 2014). "Beyond the cell lines, we have identified cytoplasmic EZH2 and complex formation between EZH2 and DLC1 in other lung cancer models, including NSCLC patient-derived xenografts and a mutant KRas mouse lung tumor model." (PMID 34862367, 2021). "Our previous results showed that resveratrol induced mitochondrial dysfunction and consequently promoted oxidative stress, then triggered senescence by upregulation of DLC1 in breast and lung cancer cells." (PMID 31968672, 2020). "DLC1 exhibits tumor suppressor activity when ectopically expressed in cancer cells and in nude mice injected subcutaneously with lung cancer cells." (PMID 28903430, 2017). "Interestingly, DLC1 downregulation abrogated the negative regulation of ectopic E-cad on RhoA activity, thereby allowing anchorage-independent growth and migration in lung cancer." (PMID 40354489, 2025). "DLC1 is a tumor suppressor in many different cancer types, including in lung cancer and could inhibit cancer cells through Rho GTPase accelerating proteins (GAP) dependent- and independent-mechanisms." (PMID 33612479, 2021). "As reported for the rat DLC1 homolog, immunoprecipitation studies confirmed complex formation between PLCD1 and DLC1 in H1703 cells, a human lung cancer cell line that expresses readily detectable levels of both proteins, as well as between PLCD1 and Caveolin-1." (PMID 34727930, 2021). "Additionally, S100A10 also regulated the metastasis of lung cancer cells by the interaction with DLC1." (PMID 34178044, 2021). "Consistent with this hypothesis, siRNAs knockdown of KRAS greatly reduced cytoplasmic EZH2 in A549 cells, which have mutant KRAS, and increased DLC1 protein in A549 and four other lung cancer lines with mutant KRAS." (PMID 34862367, 2021). "However, in a set of lung cancer cells, the complex responsible for degrading DLC-1 comprises CULT4, DDB1 and FBXW5 E3 ligases all together, thus suggesting the difference existing in the composition of E3 ligases between cancer cells and hMSCs." (PMID 33148199, 2020). "Additionally, experimental studies have shown that S100A10, a recently identified binding partner of DLC1, regulates invasion of human lung cancer cells." (PMID 31739800, 2019). "Re-expression of DLC1 in liver, breast, lung cancer cell lines inhibits cancer cell growth." (PMID 23988121, 2013). "This reduced DLC1 activity in human lung cancer was attributable to AKT and SRC kinase activities, both of which reduce the tumor suppressor activity of DLC1 via direct phosphorylation of specific tyrosines by SRC and specific serines by AKT28." (PMID 39528835, 2024). "Similar reductions of RhoA-GTP by Tazemetostat and the kinase inhibitors were observed in three other lung cancer lines (NCI-H23, NCI-H460, and SW900) that express DLC1 mRNA but lack detectable DLC1 protein." (PMID 34862367, 2021). "DLC1 is a potential tumor suppressor gene, previous research in our laboratory has shown resveratrol upregulated DLC1 expression to induce SASP and increase SA-β-gal positive stained breast and lung cancer cells." (PMID 31968672, 2020). "The methylation status of RASSF1A, CDH1, DLC1 and PRPH was analysed in BW samples from 91 lung cancer patients and 31 controls, using a novel two‐colour droplet digital methylation‐specific PCR (ddMSP) technique." (PMID 32441866, 2020). "Re-expression of Dlc1 inhibited the mobility and invasiveness of HCC, breast, ovarian and lung cancer cell lines." (PMID 22792269, 2012). "mRNA expression of the DLC1 tumor suppressor gene is downregulated in many lung cancers and their derived cell lines, with DLC1 protein levels being low or absent." (PMID 34862367, 2021).
lung carcinoma (continued). "To determine whether cytoplasmic EZH2 is frequent in lung cancer lines, we evaluated six additional lines that express DLC1 mRNA, three of which resemble A549 in not having readily detectable levels of endogenous DLC1 protein." (PMID 34862367, 2021).